IL1B (interleukin 1 beta)
Diseases named in the same sentence as IL1B in open-access papers (continued):
Sharing a sentence is not in itself a finding about the gene and the disease.
dengue (continued). "IL-1β, IFN-γ, IL-4, IL-6, IL-13, IL-7 and GM-CSF were significantly increased in patients with severe clinical manifestations (severe dengue) when compared to mild disease forms (mild dengue)." (PMID 18578883, 2008). "Many of the studies have also indicated that the levels of pro-inflammatory cytokines are elevated in severe dengue patients, such as interleukin (IL)-6, IL-8, tumor necrosis factor (TNF)-α, and IL-1β, which may result in cytokine storm and increase the severity of dengue in patients." (PMID 36235496, 2022). "Our first priority was to compare the levels of IL-1b, IL-2, IL-4, IL-6, IL-8, IL-10, IL-12p70, IL-17A, IL-33, CD14, CD54, CD62E, CD62L, CD62p, CD106, CD121b, CD154, CD178, GM-CSF, IFN-g, MIF, ST2 and TNF in plasma samples of dengue group, OF group and Healthy group." (PMID 33809042, 2021). "Notably, NS1 doesn't trigger the direct release of IL-1β, however NS1 triggers the TLR4 on platelets and amplifies the platelets response to DENV, indicating the complex interplay between host and viral factors that leads to the dengue severity." (PMID 33014899, 2020). "However, when platelets isolated from patients were incubated ex vivo, platelets from coinfected patients secreted lower levels of RANTES/CCL5 and PF4/CXCL4, but not IL-1β, compared to patients with dengue without HIV coinfection." (PMID 31068600, 2019). "But unexpectedly, we could not detect IL-1β, IL-17A or TNF-α in dengue samples because of off-target." (PMID 37024713, 2023).
Anorexia (61 papers, 2009 to 2025). Lack of desire to eat (loss of appetite). "Elevated levels of pro-inflammatory cytokines—IL-6, TNF-α, IL-1β—have been observed in depressed patients and are associated with sickness behavior (anhedonia, fatigue, anorexia), overlapping with depressive symptoms." (PMID 40927563, 2025). "For example, the Mc3r–/– mouse was demonstrated to exhibit greater anorexia and weight loss in response to LPS treatment or IL-1β treatment and greater loss of both fat mass and lean mass in response to implantation of Lewis lung carcinoma cells." (PMID 39007271, 2024). "IL-1β is implicated as a cytokine in the development of anorexia associated with chronic disease (most commonly cancer), probably mediated through elevated levels of corticotropin-releasing hormone, which inhibits food intake." (PMID 37762896, 2023). "Specifically, intracerebroventricular (ICV) injection of pathophysiological levels of interleukin 1 beta (IL-1β) or TNF-α results in anorexia, weight loss, increased energy expenditure and accelerated catabolism of fat and lean mass." (PMID 34439145, 2021). "Cytokines such as IL-1β are important players in inflammation-induced anorexia and weight loss, due to its action in the hypothalamus-pituitary-adrenal axis (HPA)." (PMID 31253122, 2019). "Here we show that ovBNST PKC-δ neurons are activated by peripheral administration of IL-1β and LPS, and chemogenetic silencing of these neurons can effectively attenuate the inflammation-associated anorexia." (PMID 31235690, 2019). "It is known that TNF-α and IL1β, are cytokines that mediates symptoms of sickness such as anorexia, immobility and body weight loss." (PMID 30133465, 2018). "To determine which IL-1β responsive cells are necessary for the resultant fever, lethargy, anorexia, and loss of body weight, we systematically eliminated Myd88-dependent signaling from identified targets." (PMID 29121947, 2017). "In contrast, conditional deletion of MyD88 from endothelial and myeloid cells (including microglia) driven by the Tie2 promoter confers resistance to anorexia, weight loss, reduced locomotor activity, and fever in response to icv IL-1β." (PMID 28668091, 2017). "We previously demonstrated that Tie2Cre-MyD88Lox/Lox mice are completely resistant to anorexia, weight loss, fever, and reduced locomotor activity in response to icv IL-1β." (PMID 28668091, 2017). "Intravenous injection of IL1β induces sickness behavior and has been directly linked to fever and anorexia." (PMID 27793136, 2016). "Potent anti-inflammatory effects of ghrelin were reported on the expression of IL-1β, IL-6, and TNFα in the liver, spleen, lungs, and mesenteric lymph nodes of LPS-treated mice associated with an attenuation of the LPS-induced anorexia." (PMID 26681840, 2015). "One potential cause of DON-induced anorexia is the induction of proinflammatory cytokines, including IL-1β, IL-6, and TNF-α, which have been previously shown to cause sickness behavior in humans and experimental animals." (PMID 26492270, 2015). "Previous studies demonstrated that intracerebroventricular injection of LPS or IL-1β induces sickness behavior, anorexia and body weight loss." (PMID 25884208, 2015). "Dramatic reductions in food intake are commonly associated with localized and systemic illness, but sickness-associated anorexia is attenuated if food is restricted prior to IL-1β administration." (PMID 25071776, 2014). "An action of the pro-inflammatory cytokine interleukin-1β (IL-1β) at central nervous system sites has been implicated in the pathogenesis of anorexia." (PMID 24314273, 2013). "Moreover, the presence of increased IL-1β is connected to the loss of muscle mass, exacerbating anorexia and escalating energy expenditure." (PMID 37755304, 2023). "We next investigated whether the activation of ovBNST PKC-δ neurons is required for inflammation-associated anorexia induced by IL-1β or LPS." (PMID 31235690, 2019).
Anorexia (continued). "Indeed, cytokines (e.g., TNF-a, IL-1a, IL-1b and IL-6) can directly cause neuronal apoptosis and produce a stereotyped cluster of nonspecific signs such as impaired concentration, anorexia, fatigue, diminished motivation, depression, and anorexia." (PMID 35964069, 2022). "Previous studies have shown that TNF-α and IL-1β play an important role in the induction of anorexia by DON and its congeners and that the use of antagonists of the TNF-α receptor as well as the IL-1β receptor also attenuates DON-induced anorexia." (PMID 39691381, 2024). "Previous experiments in a mouse model of anorexia suggested that SlrP from S. enterica serovar Typhimurium inhibited inflammasome activation and IL-1β maturation in the small intestine." (PMID 38361917, 2024). "Intracerebroventricular (ICV) injection of TNFα or IL‐1β at pathophysiological levels—aiming to administer the cytokines directly to the central nervous system—induces anorexia." (PMID 38414161, 2024). "Elevated levels of IL-1β are particularly evident in patients with cancer-related anorexia, with its severity being closely correlated to the levels of IL-1β." (PMID 37755304, 2023). "The addition of other pro-inflammatory cytokines such as Il-1b also induce the reduction in food intake and anorexia in rats." (PMID 34768822, 2021). "Djamil and colleagues demonstrated that patients with cancer-related anorexia had significantly higher levels of IL-1β than comparators and that this was correlated with severity of anorexia." (PMID 33907915, 2021). "Similar increases of IL6 and IL1β gene expressions were found in the hippocampus of young female rats in the dehydration-induced anorexia model." (PMID 33580474, 2021). "Acute inflammation activates POMC neurons, which increase melanocortin-4 receptor (MC4R) expression and POMC expression, as shown in the LPS- and IL-1β-induced anorexia model." (PMID 34899611, 2021). "Some studies have shown that endogenous IL-1β expressed in the brain mediates lipopolysaccharide (LPS)-induced anorexia by modulating the expression of cytokines in the hypothalamus." (PMID 34899611, 2021). "Released by macrophages, Interleukin 1 beta (IL-1β) has been, together with TNF-α, one of the most clinically studied cytokines, as well as being also better associated with anorexia, weight loss and sarcopenia than Interleukin 6 (IL-6)." (PMID 33202621, 2020). "A number of cytokines have been previously linked to anorexia, including IL-6, TNF-α, CXCL8, IL-1β, IL-18, IL-2, and IFN-γ." (PMID 32071269, 2020). "In this sense, our findings indicate that the acute effects of TNF-α and IL1-β on AgRP-producing neurons likely contributes to the inflammation-induced anorexia since both cytokines inhibit the activity of 35–42% of AgRP neurons recorded." (PMID 33255553, 2020). "We found that chemogenetic silencing of the ovBNST PKC-δ neurons significantly attenuates the anorexia induced by IL-1β or LPS." (PMID 31235690, 2019). "In the hypothalamus, IL-1β is reported to be responsible for the LPS-mediated anorexia and secretion of proinflammatory cytokines." (PMID 31905825, 2019). "Through increasing gene expression of anorexia-inducing proinflammatory cytokines such as interleukin-1β (IL-1β), interleukin-6 (IL-6) and tumor necrosis factor-α (TNF-α), trichothecenes exacerbate the condition of anorexia." (PMID 29535978, 2018). "Gaigé and co-workers indicated that T-2-induced anorexia correlated with IL-1β, IL-6, and TNF-α mRNA upregulation in the spleen and liver." (PMID 29710820, 2018). "Third, while both peripheral and central injection of IL-1β into rodents elicits anorexia in rodents, only central injection of IL-6 suppresses food intake." (PMID 26492270, 2015). "Central IL-1β anorexia has also been attenuated by the peripheral treatment with 5-HT2C receptor antagonists, 5-HT1A auto receptor agonists or an inhibitor of 5-HT synthesis." (PMID 24314273, 2013).
Anorexia (continued). "This is in agreement with the previous findings concerning the importance of 5-HT to IL-1β anorexia, since the hypothalamic melanocortinergic system has been shown to mediate serotonergic drug-induced hypophagia." (PMID 24314273, 2013). "It is suggested that, although 5-HT participates in IL-1β anorexia, other mechanisms recruited by IL-1β in normal rats are able to override the absence of the serotonergic hypophagic influence." (PMID 24314273, 2013). "It is known that IL-1β acts centrally to induce anorexia (by acting on neurotransmitters) and peripherally it inhibits gastric motility, gastric emptying, and gastric acid secretion." (PMID 24209779, 2013). "Alternatively, it is possible that IL-1β produces anorexia in an IL-1RI mediated, MyD88-independent manner." (PMID 23031643, 2012). "Using genetic models exhibiting impairment of LPS and IL-1β signaling, these studies have shown that this de novo central production of cytokines is required to obtain a sustained anorexia in response to LPS or IL-1β administration." (PMID 23202308, 2012). "In summary, our results shown that in the hypothalamus of sedentary tumour-bearing animals increase in TNF-α and IL-1β levels exacerbated the disturbances that affect the reduction of food intake and worsened the framework of cancer-induced anorexia." (PMID 21861927, 2011). "This is relevant because in a previous study, TNFα promoted anorexia in rodents while IL-1β promoted motivational changes, including increased social withdrawal behavior." (PMID 21167054, 2010). "IL-6 is known to stimulate protein catabolism in order to maintain glucose levels via gluconeogenesis, whereas anorexia, is largely driven by IL-1β and is known to mobilize fat stores in lieu of protein stores." (PMID 19216742, 2009). "IL-8 together with other anorectic cytokines like IL-1β can affect the food intake and anorexia." (PMID 38498144, 2024). "The production of proinflammatory cytokines is induced by infectious factors, and higher TNF-α, IL-1β and IL-6 levels affect the surrounding organs to induce disease behavior and inflammation-related anorexia, which participate in the induction of disease behavior." (PMID 34899611, 2021). "Our findings indicate that the effect of TNF-α and IL-1β, especially on the activity of AgRP-producing neurons, may contribute to inflammation-induced anorexia observed during acute inflammatory conditions." (PMID 33255553, 2020). "IL-1β decreases food intake and body weight via leptin activation in adipose tissue, but it is also able to induce anorexia independently from leptin, by induction of the melanocortin system in the hypothalamus (the main area in the brain regulating feeding behavior and body weight)." (PMID 33202621, 2020). "Elevated tissue IL-1β might be more important to DON-induced anorexia than the observed IL-6 increase for several reasons." (PMID 26492270, 2015). "IL-1β-induced anorexia may depend on interactions of the cytokine with neuropeptides and neurotransmitters of the central nervous system control of energy balance and serotonin is likely to be one catabolic mediator targeted by IL-1β." (PMID 24314273, 2013). "In a previous study, we used brain microdialysis to address the question of whether the 5-HT system in the ventromedial hypothalamus (VMH) participates in the anorexia induced by IL-1β in obese Zucker rats." (PMID 24314273, 2013). "IL-1β and IL-6 are regarded as the key pro-inflammation cytokines triggering the acute phase reaction in the liver and modifying the brain-controlled functions such as fever and anorexia." (PMID 24345215, 2013). "Consistent with this, mice lacking the MC4R resist IL-1β induced anorexia, demonstrating that alterations in melanocortin signaling underlie changes in feeding in response to IL-1β." (PMID 23031643, 2012).
Anorexia (continued). "Studies suggest the cytokines IL-1β and TNF-α play a role in the neuroendocrine regulation of appetite as increased levels of these cytokines in the brain are associated with a greater incidence of anorexia in mouse models, and inhibition of TNF-α in rats was shown to forestall anorexia." (PMID 38254849, 2024). "Furthermore, the effector SlrP (Salmonella leucine‐rich repeat protein), secreted through both T3SSs, inhibits inflammasome activation and IL‐1β release in the small intestine; higher IL‐1β levels during infection with a ΔslrP strain promote anorexia and increases disease severity." (PMID 32185892, 2020). "Furthermore, intracerebroventricular co-infusion of IL-6 and IL-1β in doses that do not affect food intake when administered individually causes anorexia." (PMID 33255553, 2020). "Therefore, it might be speculated that anorexia induction by trichothecenes could be mediated by the pro-inflammatory cytokines IL-1β, IL-6, and TNF-α as part of sickness behavior." (PMID 29710820, 2018). "Intracerebroventricular (ICV) administration of 10 ng IL-1β causes fever, anorexia, lethargy, and weight loss without raising circulating levels of IL-1β, and sickness responses triggered by peripheral inflammation are blocked by ICV administration of the endogenous IL-1 receptor antagonist (Il1ra)." (PMID 29121947, 2017). "IL-1β itself may be the ultimate mediator of inflammation-induced anorexia." (PMID 23031643, 2012). "Moreover, the sensitivity to IL-1β-induced anorexia was decreased in food-restricted rats." (PMID 20953376, 2010). "Inflammatory cytokines interfere with hypothalamic appetite control, particularly in the arcuate nucleus: IL-1β and TNF-α reduce neuropeptide Y (NPY) and agouti-related peptide (AgRP), leading to anorexia." (PMID 40927563, 2025). "Tumour-driven cytokines, such as growth differentiation factor 11, IL-1β, IL-6 leukaemiaia inhibitory factor, TNF-α, and TGFβ1 promote cancer cachexia with anorexia in the brain, proteolysis in the skeletal muscles, and browning in the WAT." (PMID 35406121, 2022). "Increases in IL-1β and TNF contribute to anorexia, and TNF and IL-6 promote lipolysis and inhibit lipogenesis in WAT leading to weight loss." (PMID 32934774, 2020). "Elevations of IL-1β, IL-6, and TNF-α were observed in DON-administered mice that were correlated to DON-induced anorexia." (PMID 29710820, 2018). "Lipopolysaccharide (LPS) - or muramyl dipeptide-induced anorexia increased hypothalamic gene expression of several cytokines and central administration of MCP1, RANTES, IL-8, or IL-1β has been shown to decrease food intake." (PMID 25427253, 2014). "Thus, a specific increase of IL-1β in CX3CR1-/- mice without a concomitant exaggeration of TNFα may enhance the behavioral effects of LPS without causing exaggerated anorexia and weight loss." (PMID 21167054, 2010). "Although, the anti-inflammatory drug indomethacin, which has been shown to prevent IL-1β-induced anorexia, did not affect food intake during influenza virus infection." (PMID 32071269, 2020). "Accumulating evidence indicates that systemic inflammation and pro-inflammatory cytokines, including TNF-β, IL-6 and IL-1β, are major factors in promoting muscle atrophy through UPS activation, muscle differentiation and myogenesis inhibition, and improvement of anorexia during cancer cachexia." (PMID 29731967, 2018). "Although MyD88 expression in neurons has been suggested to play a critical role in the behavioral response to inflammation, we find that IL-1β induced anorexia and lethargy is not contingent upon MyD88-expression in both neurons and astrocytes." (PMID 23031643, 2012). "We posit that cerebrovascular cells or perivascular macrophages/microglia are the most likely targets for IL-1β signaling in the brain, implying that systemic therapy addressing anorexia and fatigue need not penetrate the blood brain barrier." (PMID 23031643, 2012).
Anorexia (continued). "Surprisingly, the outcome of lessening IL-1β signaling on DON-induced anorexia has not been tested to date." (PMID 23202308, 2012). "Additionally, a study using the dehydration-induced anorexia model, elevated levels of the inflammatory markers were reported (TNF-α, IL-6, and IL-1β), suggesting the possibility of an environment conducive to neuroinflammation with suggested correlation with neurodegeneration." (PMID 40269196, 2025). "Both IL-1β and TNF-α receptor antagonists could weak the DON-induced anorexia." (PMID 39691381, 2024). "In addition, exogenous IL-1β and TNF-α did not induce anorexia individually, but did so when administered simultaneously by causing neuroendocrine changes." (PMID 24209779, 2013).